RN7SL386P (RNA, 7SL, cytoplasmic 386, pseudogene)
Gene: Miscellaneous RNA gene on chromosome 1 (21,987,481 to 21,987,777, forward strand). Ensembl gene ENSG00000273610.
Homologues: Orthologues: chimpanzee Metazoa_SRP (99% identical), macaque Metazoa_SRP (81% identical). Paralogues in human: RN7SL186P (99% identical), RN7SL1 (86% identical), RN7SL2 (85% identical), RN7SL3 (84% identical), RN7SL45P (84% identical), RN7SL126P (83% identical), RN7SL679P (82% identical), RN7SL660P (81% identical), RN7SL712P (81% identical), RN7SL778P (81% identical), RN7SL296P (81% identical), RN7SL383P (81% identical), and 703 more.